Y_RNA (Y RNA )
Gene: Miscellaneous RNA gene on chromosome 14 (49,839,401 to 49,839,493, reverse strand). Ensembl gene ENSG00000277634.
Homologues: Paralogues in human: Y_RNA (71% identical), Y_RNA (70% identical), RNY3 (69% identical), Y_RNA (69% identical), Y_RNA (68% identical), RNY3P16 (67% identical), RNY3P4 (67% identical), Y_RNA (67% identical), RNY3P1 (66% identical), RNY3P2 (66% identical), RNY3P9 (66% identical), Y_RNA (66% identical), and 82 more.